RN7SL415P (RNA, 7SL, cytoplasmic 415, pseudogene)
Gene: Miscellaneous RNA gene on chromosome 6 (91,739,609 to 91,739,897, forward strand). Ensembl gene ENSG00000240961.
Homologues: Orthologues: chimpanzee Metazoa_SRP (99% identical), macaque Metazoa_SRP (95% identical). Paralogues in human: RN7SL1 (83% identical), RN7SL2 (83% identical), RN7SL3 (82% identical), RN7SL11P (81% identical), RN7SL336P (81% identical), RN7SL296P (81% identical), RN7SL126P (80% identical), RN7SL88P (80% identical), RN7SL218P (80% identical), RN7SL712P (80% identical), RN7SL178P (79% identical), RN7SL49P (79% identical), and 703 more.